ACSF2 (acyl-CoA synthetase family member 2)
Description:
Acyl-CoA synthases catalyze the initial reaction in fatty acid metabolism, by forming a thioester with CoA. Has some preference toward medium-chain substrates. Plays a role in adipocyte differentiation.
Synonyms: FLJ20920; ACSMW; AVYV493
Tractability: PROTAC: its protein half-life has been measured.
Gene: Protein-coding gene on chromosome 17 (50,426,158 to 50,474,845, forward strand). Ensembl gene ENSG00000167107.
Subcellular location: Mitochondrion
Subcellular location (Human Protein Atlas): Cytosol; Microtubules; Nucleoplasm
Pathways (Reactome):
Metabolism: Mitochondrial Fatty Acid Beta-Oxidation
Gene Ontology:
Molecular function: medium-chain fatty acid-CoA ligase activity; protein binding; long-chain fatty acid-CoA ligase activity; catalytic activity
Biological process: acyl-CoA metabolic process; long-chain fatty acid metabolic process
Cellular component: mitochondrion; mitochondrial matrix
Genetic constraint (gnomAD): Loss-of-function variants: 52 observed, 77.6 expected, observed/expected ratio (o/e) 0.67, 90% interval 0.54 to 0.84. The upper end of that interval is the gene's LOEUF score, 0.84, which puts it in group 3 of 6, group 1 being the genes least tolerant of losing a copy. Missense variants: 660 observed, 807.57 expected, observed/expected ratio (o/e) 0.82, 90% interval 0.77 to 0.87. Synonymous variants: 283 observed, 315.23 expected, observed/expected ratio (o/e) 0.9, 90% interval 0.81 to 0.99.
Homologues: Orthologues: chimpanzee ACSF2 (99% identical), macaque ACSF2 (94% identical), rabbit ACSF2 (85% identical), guinea pig ACSF2 (80% identical), rat Acsf2 (80% identical), dog ACSF2 (79% identical), mouse Acsf2 (79% identical), pig ACSF2 (74% identical), tropical clawed frog acsf2 (56% identical), zebrafish acsf2 (54% identical), Drosophila melanogaster Acsf2 (37% identical). Paralogues in human: ACSS1 (21% identical), ACSF3 (20% identical), ACSM4 (20% identical), ACSM5 (20% identical), ACSM1 (19% identical), ACSM2A (19% identical), ACSM2B (19% identical), ACSM3 (19% identical), ACSS2 (18% identical), ACSS3 (17% identical), AACS (17% identical), AASDH (16% identical), and 1 more.
Diseases named in the same sentence as ACSF2 in open-access papers:
ACSF2 is named in the same sentence as 26 diseases in open-access papers, as found by Europe PMC text mining. Sharing a sentence is not in itself a finding about the gene and the disease. The quoted sentences say what the papers report.
breast carcinoma (5 papers, 2016 to 2024). "Out of the 60 ferroptosis-related genes, 9 were of prognostic value in breast cancer, of note, only ACSF2 presented as a favorable prognostic factor." (PMID 33672990, 2021).
acute kidney injury (2 papers, 2024). Sudden and sustained deterioration of the kidney function characterized by decreased glomerular filtration rate, increased serum creatinine or oliguria. "Inhibition of ACSF2 in Human renal cortex proximal convoluted tubule epithelial cells-2 (HK-2) cells has been shown to reduce cellular lipid peroxidation, enhance mitophagy, restore mitochondrial function, and protect against ischemia-reperfusion–induced acute kidney injury." (PMID 39916955, 2024).
diabetic nephropathy (2 papers, 2025). "The mitochondrial localization of acyl-CoA synthetase family member 2 (ACSF2) K182la can promote mitochondrial dysfunction in high-glucose-treated HK-2 cells, potentially leading to diabetic nephropathy." (PMID 40563450, 2025).
renal carcinoma (2 papers, 2024 to 2025). A carcinoma arising from the epithelium of the renal parenchyma or the renal pelvis. "[PubMed keyword research: (((ACSF2) AND (kidney)) OR (renal carcinoma)) OR (renal cell carcinoma)]." (PMID 38534739, 2024). "Furthermore, ACSF2 was found to be significantly downregulated in most tumors, particularly in renal cancer." (PMID 38534739, 2024). "In addition, we found that ACSF2 is a potential prognostic factor for renal cancer." (PMID 38534739, 2024).
ulcerative colitis (2 papers, 2025). An inflammatory bowel disease involving the mucosal surface of the large intestine and rectum. "The results indicate that the differential expression of ACSF2 and SLC7A5 may serve as valuable biomarkers for the early diagnosis of ulcerative colitis." (PMID 40729322, 2025).
kidney cancer (1 paper, 2024). Primary or metastatic malignant neoplasm involving the kidney. "Notably, ACSF2 was found to have a positive association with LINC01020 expression in three types of kidney cancer (KIRP r = 0.90, p < 0.0001, KICH r = 0.81, p < 0.0001, KIRC r = 0.69, p < 0.0001)." (PMID 38534739, 2024). "The ACSF2-LINC01020 pair was found to have a strong correlation in kidney cancer, suggesting that ACSF2 may potentially promote ferroptosis in KIRP." (PMID 38534739, 2024). "However, no studies have investigated the role of ACSF2 in kidney cancer." (PMID 38534739, 2024).
kidney tumor (1 paper, 2024). "Until now, no studies have reported the role of ACSF2 or LINC01020, or their interaction, in ferroptosis or kidney tumor prognosis." (PMID 38534739, 2024).
metastatic melanoma (1 paper, 2023). A melanoma that has spread from its primary site to another anatomic site. "ACSF2 may participate in metastatic melanoma by regulating ferroptosis." (PMID 38155938, 2023).
Obesity (1 paper, 2023). Accumulation of substantial excess body fat. "A total of 175 genes including thermogenic markers (UCP2, CKMT2, and CITED1) and 5 BATLAS markers (PPARGC1B, ACO2, ACSF2, NNAT, and DMRT2) were expressed less in active beige adipocytes carrying FTO obesity-risk variant as compared to risk-free carriers." (PMID 37416800, 2023).
ovarian carcinoma (1 paper, 2021). A malignant neoplasm originating from the surface ovarian epithelium. "Specifically, a 10-gene signature (HIC1, ACSF2, MUC1, etc.)was developed for the diagnosis of ovarian cancer with high sensitivity using LASSO regression." (PMID 35071242, 2021). "A reliable 10-gene ferroptosis signature (HIC1, ACSF2, MUC1, etc.)for the diagnosis of ovarian cancer was identified." (PMID 35071242, 2021).
psoriasis (1 paper, 2022). An autoimmune condition characterized by red, well-delineated plaques with silvery scales that are usually on the extensor surfaces and scalp. "Among them, PEBP1, PRKAA2 and ACSF2 are associated with ferroptosis and participate in regulating immune microenvironment in psoriasis cases." (PMID 36685512, 2022). "Besides, based on CIBERSORT analysis, alterations of immune microenvironment in psoriasis cases were possibly associated with PRKAA2, PEBP1, CISD1, and ACSF2." (PMID 36685512, 2022). "Typically, CISD1 (p = 3.9e-10), TRIB2 (p < 2.22e−16), and ABCC5 (p=0.0012) levels among psoriasis cases increased compared with healthy controls, whereas PRKAA2 (p < 2.22e−16), ACSF2 (p = 3e−15), TIMM9 (p= 0.049), PEBP1 (p < 2.22e−16) and NR5A2 (p=1.8e−13) levels decreased among psoriasis cases." (PMID 36685512, 2022).
psychosis (1 paper, 2019). "Bioinformatic analysis of WES and CGH-array data selected 15 common for psychosis phenotype damaging variants and 6 of them were rare mutations, including paternal 3p26.3-loss and 5 additional missense mutations located in ACSF2, MPRIP, PHC1, PER3, and RERE genes." (PMID 30710087, 2019).
renal cell carcinoma (1 paper, 2024). "Thus, ACSF2 might play a crucial role in regulating ferroptosis in renal cell carcinoma." (PMID 38534739, 2024).
Sepsis (1 paper, 2024). Sepsis is defined as life-threatening organ dysfunction caused by a dysregulated host response to infection. "Downregulation of MALAT1 restrained sepsis‐induced ferroptosis in renal cells by recruiting the RNA binding protein FUS to reduce the stability of acyl‐CoA synthetase family member 2 (ACSF2) mRNA." (PMID 39390627, 2024). "Therefore, we further explored whether MALAT1 affected ferroptosis during sepsis‐induced AKI through regulation of ACSF2." (PMID 39390627, 2024).
tumor (9 papers, 2015 to 2024). "ACSF2 was found to be among ferroptosis regulators in a signature, used to distinguish UM patients with different overall survival, that defined two clusters of patients with differences in prognosis and tumor-microenvironment-infiltrating cells." (PMID 38339073, 2024). "The expression levels of ACSL1 and ACSF2 were higher in tumor tissues than in normal tissues." (PMID 39524444, 2024). "We detected marked differences in the immunohistochemical staining of two key proteins, ACSF2 and ACSL1, between tumor tissue samples and normal tissue samples." (PMID 39524444, 2024). "Then, the expression level of AACS (p < 0.05) and ACSF2 (p < 0.05) were remained significantly raised in HCC tissues according to GEPIA database, but the expression level of AASDH was reduced in tumor tissues than in normal tissues." (PMID 36205594, 2022). "Although SLC25A5, ACSF2, MFF, and PMAIP1 have not been previously linked to PE, they are known to significantly influence mitochondrial function and tumor cell death." (PMID 39916955, 2024). "Among these ten genes, the expression levels of SETD1B, ACSF2, MUC1, KLHL24, PML, MT1G, and GPT2 were higher in tumor tissues than those in normal tissues, while HIC1, AKR1C1, and LOC390705 were lower expressed in tumor tissues." (PMID 35071242, 2021). "Furthermore, ferroptosis-related genes with copy number amplification (including FADS2, NQO1, ABCC1, ACSF2, HMOX1, FANCD2 and SQLE) demonstrated higher expression in tumour tissues, and those with copy number deletion (including CRYAB, ACSL3, ZEB1) demonstrated lower expression in tumour tissues." (PMID 35145965, 2022). "IHC demonstrated the upregulation of ACSF2, MTMR9, and CPNE3 in BRCA tissues, whereas ACSL1 expression was not significantly different between tumor tissues and adjacent tissues." (PMID 39524444, 2024).
cancer (5 papers, 2023 to 2024). A tumor composed of atypical neoplastic, often pleomorphic cells that invade other tissues. "Next, we analyzed the differential expression of KIRP in pan-cancer and found that the expression of ACSF2 was low in all three types of RCC." (PMID 38534739, 2024). "We also utilized GEO data and conducted pan-cancer analysis to validate the ferroptosis gene ACSF2 as a novel negative regulator of ferroptosis induction." (PMID 38534739, 2024). "We hypothesize that ACSF2 may protect the body from tumors by acting as a cancer suppressor, which needs further research." (PMID 38534739, 2024). "In addition to the ACSL family, ACSF2 has been reported to be a ferroptosis-related gene, which is correlated with poor prognosis in cancer, while the specific mechanism of ACSF2 on ferroptosis-related cancers remains unclear." (PMID 38459004, 2024). "EPHX2, ACSF2, CYP27A1, ACSS1, and ALDH1L1 showed hypermethylation in several types of human cancer; on the contrary, AKR1B10, POLG2, NDUFB8, ACACB, and MRPS22 consistently showed hypomethylation in several types of human cancer." (PMID 37223030, 2023).
infection (1 paper, 2021). The state of being infected such as from the introduction of a foreign agent such as serum, vaccine, antigenic substance or organism. "The two DRPs identified at 24 h post-infection, ACSF2 and NONO, did not yield pathway enrichment results." (PMID 34079533, 2021).
ACSF2 also shares sentences with these, for which no sentence is quoted: Nephropathy (2 papers); brain cancer (1); Cognitive impairment (1); deep vein thrombosis (1); gestational diabetes (1); Insulin resistance (1); prostate carcinoma (1); retinopathy (1); type 2 diabetes (1).